CYP2A6 (cytochrome P450 family 2 subfamily A member 6)
Diseases named in the same sentence as CYP2A6 in open-access papers (continued):
Sharing a sentence is not in itself a finding about the gene and the disease.
nicotine dependence (29 papers, 2005 to 2025). Physical and psychological dependence on nicotine. "Among regular smokers, nicotine dependence is linked to CYP2A6 genotype and metabolism rate, with reduced-function alleles or slower CYP2A6 activity (lower NMR quartiles) associated with lower nicotine dependence and fewer cigarettes per day." (PMID 40126262, 2025). "The most common trait that was associated with CYP2A6 was related to smoking behaviors, such as tobacco use, cigarettes smoked per day, nicotine metabolite ratio, smoking status, cotinine levels, nicotine dependence, and smoking cessation." (PMID 39457450, 2024). "The correlation between CYP2A6 activity, nicotine metabolism, and smoking led researchers to investigate the role of various genetic CYP2A6 polymorphisms in nicotine addiction." (PMID 39125600, 2024). "For Caucasian individuals, the CYP2A6 slow inactivator genotype increased the risk of nicotine dependence when smoking was initiated during adolescence." (PMID 28472995, 2017). "Differences in nicotine metabolism and risk of nicotine addiction have been attributed to functional allelic variation in cyp2a6." (PMID 28536537, 2017). "Among adult regular smokers, nicotine dependence is associated with CYP2A6 genotype and the rate of nicotine metabolism, however findings are inconsistent." (PMID 29194389, 2017). "The normal nicotine metabolizer CYP2A6*1A is associated with high scores of nicotine dependence on the Fagerström Test for Nicotine Dependence (FTND) scale because it encodes for enzymes that catalyze nicotine 100%." (PMID 26060595, 2015). "The slow nicotine metabolizer alleles of CYP2A6 catalyze less nicotine and positively influence nicotine-dependence treatment." (PMID 26060595, 2015). "For example, the interaction between nicotine and the CYP2A6 polymorphism CYP2A6∗1A (normal nicotine metabolizer) leads to nicotine addiction." (PMID 26060595, 2015). "The fully functional allele CYP2A6*1A metabolizes enough nicotine each time a tobacco user inhales the smoke of cigarette to lead to nicotine dependence." (PMID 26060595, 2015). "The role of CYP2A6 polymorphism is a determinant in the development of nicotine dependence and its treatment." (PMID 26060595, 2015). "This study provides preliminary results regarding the effect of the SLC6A3 VNTR, ANKK1/DRD2 TaqIA, and CYP2A6*4 polymorphisms on smoking cessation and nicotine dependence in a Japanese population." (PMID 25526961, 2014). "The present study also examined the effect of smoking history (age at which the participant began smoking and duration of smoking) on the association between SLC6A3, ANKK1/DRD2, and CYP2A6 polymorphisms and nicotine dependence." (PMID 25526961, 2014). "The gene with highest absolute weight in the gamma-Hexachlorocyclohexane degradation pathway, CYP2A6, plays a key role in nicotine metabolism and has been linked to nicotine dependence." (PMID 16156896, 2005). "Additionally, two markers in CHRNA5 (rs16969968) and CYP2A6 (rs1801272) genes, associated with increased risk for nicotine dependence in smokers, were proven to be carried by the Saudis involved in our study." (PMID 40376268, 2025). "CYP2A6 encodes the primary enzyme responsible for nicotine metabolism, which can affect the concentration and duration of nicotine exposure in the blood, thereby associating with nicotine addiction and abstinence outcomes in smokers." (PMID 37251809, 2023). "Higher CYP2A6 activity is associated with nicotine dependence and could be regulated through DNA methylation." (PMID 33375250, 2020). "The genetic variability of CYP2A6 directly influences the range of nicotine metabolism in the body, which can indirectly affect the reinforcing and aversive nicotine properties in the brain and can change the individual risk of nicotine dependence." (PMID 28507465, 2017).
nicotine dependence (continued). "This goal can be realized through studies that may provide accurate assessment through multivariable analyses of CYP2A6 genes variants in correlation with nicotine dependence and withdrawal syndrome, other genes, and different forms of therapies." (PMID 26060595, 2015). "A correlational study could also help examine to what extent CYP2A6 major variants are correlated with other nicotine dependence risk factors and how they can influence nicotine dependence treatment." (PMID 26060595, 2015). "CYP2A6 polymorphisms might mediate the association between the 10r/10r genotype and low nicotine dependence." (PMID 25526961, 2014). "This study examined whether functional polymorphisms in SLC6A3, ANKK1/DRD2, and CYP2A6 affect smoking cessation and nicotine dependence in a Japanese population." (PMID 25526961, 2014). "Because heavy smoking (high HSI score) was more frequent among individuals carrying the CYP2A6 *1 allele, these results might indicate an association between the CYP2A6 polymorphism and high nicotine dependence." (PMID 25526961, 2014). "Our results suggested that the age at which current smokers began smoking might moderate the effect of SLC6A3 and CYP2A6 polymorphisms on nicotine dependence." (PMID 25526961, 2014). "The expression of different variants of the CYP2A6 gene, coding for enzymes with different catalytic activities, influences the level of cotinine achieved in the body after nicotine consumption and, seems to influence nicotine addiction." (PMID 23087643, 2012). "An overview of CYP2A6 polymorphism enzymatic activities in nicotine dependence etiology and treatment revealed that slow nicotine metabolizers may strengthen the individualized treatment of nicotine dependence." (PMID 26060595, 2015). "Different emotion, sleep deficiency, caffeine intake, alcohol consumption, mental activities after dinner, physical exercises and CYP2A6 genotype have an effect on daily smoking and nicotine dependence." (PMID 38223627, 2023). "Given positive preliminary evidence for the use of a candidate gene score for CYP2A6, this approach has promise for use in treatment of nicotine dependence." (PMID 37359362, 2023). "There are differences in the genotype frequencies of SNPs in genes related to nicotine metabolism (CYP2A6) and nicotine dependence (NRXN1, DRD4, CHRNA3-CHRNA5)." (PMID 34205269, 2021). "Previously, we had reported other SNPs in smoking-related genes as NRXN1, DRD4, HTR2A, CHRNA3, CHRNA5, and CYP2A6 in Mexican mestizo, focused on smokers enrolled in a smoking cessation program, mostly with high tobacco consumption and nicotine dependence." (PMID 34205269, 2021). "Earlier studies reported that CYP2A6 enzyme activity affected nicotine dependence and cigarette consumption." (PMID 33329709, 2020). "The noticeable temporal effect of CYP2A6 on smoking behavior and nicotine dependence necessitates further research." (PMID 29724170, 2018). "The review further aims to consider CYP2A6 in future studies as a possible genetic marker for the prevention and treatment of nicotine addiction." (PMID 28507465, 2017). "As a result, carriers of CYP2A6*2A are poor nicotine metabolizers, smoke less, and recover quickly following nicotine dependence treatment." (PMID 26060595, 2015). "This review describes the natural products that have been studied as CYP2A6 inhibitors commenting on their action and highlighting their potential as a cost-efficient way to reduce nicotine addiction, either as stand-alone products or in combination with other NRT strategies." (PMID 39125600, 2024). "Genotyping results suggested that nicotine dependence among current smokers homozygous for the SLC6A3 10r allele was lower than that of smokers carrying the minor alleles, and that the CYP2A6 polymorphism might mediate this association." (PMID 25526961, 2014).
nicotine dependence (continued). "The genotyping results suggest that nicotine dependence in current smokers who are homozygous for the SLC6A3 10r allele was lower than that in individuals carrying the minor alleles, and that CYP2A6 polymorphisms might mediate this association." (PMID 25526961, 2014). "Comparisons of Fagerstrom Test for Nicotine Dependence (FTND), Physiological Cigarette Dependence Scale (PCDS), and Cigarette Withdrawal symptoms (CWS-21) among the smokers with different CYP2A6/COMT polymorphisms were not significantly different." (PMID 28472995, 2017). "In several investigations, smokers with CYP2A6 reduce-of-function genotypes or slower CYP2A6 activity (lower NMR quartiles) exhibited lower FTND (Fagerström Test for Nicotine Dependence) scores, a measure of the degree of nicotine dependence, compared to faster nicotine metabolizers." (PMID 29194389, 2017). "In that study, we reported that genetic variants of the drug transporter ABCB1 and a particular haplotype (1236TT-2677TT-3435TT) were significantly associated with non-smoking status, while no other associations with genetic variants of ABCB1 or CYP2A6, CYP2B6 with nicotine addiction was found." (PMID 35222535, 2022). "In the Pharmacogenetics of Nicotine Addiction Treatment clinical trial (NCT0131001), participants were randomized to treatment groups (placebo, nicotine patch, or varenicline) using prospective stratification based on their pretreatment NMR (representative of their CYP2A6 enzyme activity)." (PMID 29194389, 2017). "We found that current smokers with the SLC6A3 10r/10r genotype were more likely to have low nicotine dependence, based on HSI analysis, although the genotypic differences between current and former smokers were not significant for any of the SLC6A3, ANKK1/DRD2, and CYP2A6 polymorphisms tested." (PMID 25526961, 2014). "We found that current smokers with the 10r/10r genotype were more likely to have low nicotine dependence based on HSI analysis, although the genotypic differences between current and former smokers were not significant for any of the SLC6A3, ANKK1/DRD2, and CYP2A6 polymorphisms." (PMID 25526961, 2014).
breast carcinoma (12 papers, 2004 to 2025). "Comparing only smoker groups, the frequencies of XRCC1, APEX1, XPD, CYP2A6*2 and CYP2A6*9 genetic polymorphisms were similar in both controls and breast cancer patients." (PMID 27754415, 2016). "It remains to be seen if this impact of CYP2A6 genetic variation on letrozole metabolism and clearance significantly impacts treatment efficacy and response in breast cancer patients." (PMID 29194389, 2017). "We found that expressions of certain CYP genes is correlated with node status (N stage) of breast cancer including CYP2A6 (p-value = 0.025), CYP2C8 (p-value = 0.035), CYP2D6 (p-value = 0.027), CYP2J2 (p-value = 0.036), CYP3A7 (p-value = 0.026), and CYP4B1 (p-value = 0.046)." (PMID 28684774, 2017). "Among our top ranking genes for predicted breast cancer drugs are CYP2A6, and CYP2C19." (PMID 22346740, 2012). "CYP2A6 and GSTA1 are both involved in metabolic activation of several procarcinogens, and thus have been linked (in expression levels or genotypes) to the etiology of cancers such as tobacco-related lung cancer, colorectal cancer and breast cancer." (PMID 29177108, 2012). "In contrast, the catalytic activity of the CYP2A6-specific coumarin hydroxylation varied in four measured breast cancer microsomes between 1.6 and 4 pmol min−1 mgprotein−1, whereas in human liver microsomes this activity was approximately 24 nmol min−1 mgprotein−1." (PMID 14970873, 2004). "In MCF-7 breast cancer cells, multiple CYP450 isoforms were identified, including CYP2A6, CYP2A13, and CYP2J2, albeit at lower sequence coverages ranging from 1% to 7%." (PMID 41174467, 2025). "Breast cancer models, particularly MCF-7 cells, exhibited a different CYP450 profile, with CYP2J2, CYP2S1, CYP2A6 and CYP2A13 being the most prominent isoforms." (PMID 41174467, 2025). "For instance, CYP4Z2P maintains the stemness of breast cancer cells, and pseudogene CYP2A7 affects CYP2A6 expression in human liver." (PMID 33931030, 2021). "However, more research is needed to better understand the molecular roles of CYP2A6 and CYP2A7 in breast cancer." (PMID 40860340, 2025). "Lower expression of CYP2A6 and CYP2D6, involved in the metabolism of tamoxifen, tegafur and CPA may result in inefficient metabolism/activation of these agents which may affect survival of breast cancer patients as demonstrated in the current study." (PMID 33809117, 2021).
colorectal cancer (8 papers, 2012 to 2023). A primary or metastatic malignant neoplasm that affects the colon or rectum. "In humans, expression of CYP2A6 and of various CYP2A6 polymorphisms have been linked to higher rates pancreatic and colorectal cancer but to mostly reduced rates of lung and oesophageal cancer." (PMID 34628485, 2022). "High enzymatic activity of CYP2A6 has been associated with lung, esophageal and colorectal cancer." (PMID 24651674, 2014). "CYP2A6 appears to activate several procarcinogens such as hexamethylphosphoramide, 4-(methylnitrosamino)-1-(3-pyridyl)-1-butanone (NNK) and aflatoxin B1, and studies have shown that the CYP2A6 activity is associated with pancreatic cancer and colorectal cancer." (PMID 29177108, 2012).
hepatocellular carcinoma (8 papers, 2017 to 2023). A malignant tumor that arises from hepatocytes. "CYP2A6 is a CYP450 gene and has been reported its downregulation in tumor tissues is linked to worse overall survival and recurrence-free survival from hepatocellular carcinoma." (PMID 37051536, 2023). "Cytochrome P450 2A6 (CYP2A6) is an important metabolic enzyme and is involved in the progression of hepatocellular carcinoma (HCC)." (PMID 33455085, 2021). "According to our results, we cautiously drew the conclusion that downregulation of CYP2A6 and CYP2C8 in tumor tissues is linked to worse overall survival and recurrence-free survival from hepatocellular carcinoma." (PMID 30148168, 2018). "In addition to drug metabolism, CYP2A6 was reported to be involved in hepatocellular carcinoma by contributing to immune regulation." (PMID 34576282, 2021). "We examined whether SSCR regulates the expression of CYP2A6 transcriptionally in HepG2 hepatoma cells and A549 lung cells." (PMID 30662513, 2018). "In hepatocellular carcinoma (HCC), a gene conversion event between CYP2A6 and its pseudogene (CYP2A7) results in the CYP2A61B polymorphism, which carries a fragment from CYP2A7 in the 3′ UTR region." (PMID 37627052, 2023). "Then, we treated hepatoma cells with TSIIA to verify the regulation of CYP2A6, and the results showed that TSIIA increased the expression of CYP2A6 in Hep1‐6 cells cultured in vitro." (PMID 33455085, 2021). "We found that the expression level of CHRNA4 and nicotine metabolism genes, including CYP2A6, FMO3, UGT2B7 were dramatically down-regulated in human hepatocellular carcinoma, suggesting disrupted nicotine metabolism in hepatocellular carcinoma." (PMID 28583088, 2017). "Although some evidence has suggested that individuals with reduced metabolic function of CYP2A6 smoke fewer cigarettes and have a shorter smoking duration, the functionality of CHRNA4 in both normal liver and hepatocellular carcinoma still need to be further intensively investigated." (PMID 28583088, 2017).
gastric cancer (7 papers, 2011 to 2025). A primary or metastatic malignant neoplasm involving the stomach. "Our study found a significant association between CYP2A6 deletion with decreased risk of gastric cancer in Japanese female." (PMID 32131765, 2020). "When male and female were separately analyzed, CYP2A6 deletion associated with decreased gastric cancer risk in female (OR = 0.49, 95%CI: 0.25–0.95, p = 0.021, after adjustment for age, smoking and drinking)." (PMID 32131765, 2020). "Only, CYP2A6 deletion significantly associated with decreased risk of gastric cancer presence in crude analysis (p = 0.036), and remained positive after adjustment (p = 0.021)." (PMID 32131765, 2020). "To identify predictive markers for gastric cancer treatment in Chinese patients, we evaluated the association between polymorphisms of the gene encoding cytochrome P450 2A6 (CYP2A6) and outcomes of S-1 plus oxaliplatin (SOX) chemotherapy treatment." (PMID 28811232, 2017). "Indeed, one Japanese study employing 120 gastric cancer patients and 158 controls has shown that CYP2A6 deletion homozygotes increase gastric cancer risk, which appears to be contradictory to our results." (PMID 32131765, 2020). "To evaluate the effect of ALA and SFC on the human gastric cancer cell line MKN28, we determined the levels of the mRNA encoding CYP2A6, which converts tegafur to 5-FU." (PMID 26181717, 2015). "A recent investigation reported a correlation between the CYP2A6 genotype and efficacy of S-1-based chemotherapy in advanced gastric cancer." (PMID 21326246, 2011). "CYP2A6 deletion may associate with decreased gastric cancer in female and decreased total cancer in nonsmoking female." (PMID 32131765, 2020). "Similarly, following surgery, the relapse-free survival of gastric cancer patients receiving S-1 treatment was higher in those without CYP2A6 variant genotypes, compared to patients with CYP2A6 genetic variants." (PMID 29194389, 2017).
liver cancer (4 papers, 2017 to 2024). An epithelial or non-epithelial malignant neoplasm that arises from the liver. "In particular, the expression of CYP2A6 decreased dramatically in patients with macrovascular metastases and severe liver inflammation, suggesting that CYP2A6 is mainly affected by the progression of liver cancer and is involved in the inflammatory microenvironment of HCC." (PMID 33455085, 2021). "TSIIA increases the activation and polarization of macrophages through CYP2A6, which may help to achieve the goal of treating liver cancer." (PMID 33455085, 2021). "The close relationship between CYP2A6 and clinical parameters makes it have the potential to become a new biomarker for HCC, and it is also one of the effective therapeutic targets for liver cancer patients." (PMID 33455085, 2021).
neutropenia (4 papers, 2011 to 2017). A decrease in the number of neutrophils found in the blood. "As for CYP2A6, the presence of variant alleles (*4, *7, *9, or *10) was associated with leukopenia (p for tend = 0.022), but not with neutropenia (p for trend = 0.161)." (PMID 28347333, 2017).
Obesity (4 papers, 2022 to 2024). Accumulation of substantial excess body fat. "Furthermore, three human CYP2A6 single nucleotide polymorphisms are associated with obesity providing further evidence that the lack of CYP2A6 is obesogenic." (PMID 36611876, 2022). "Studies have found that HHIP (hedgehog interacting protein), MUC5AC, CYP2A6, and PCK1 can promote obesity." (PMID 38137330, 2023).